IL6 (interleukin 6)
Diseases named in the same sentence as IL6 in open-access papers (continued):
Sharing a sentence is not in itself a finding about the gene and the disease.
pulmonary hypertension (continued). "Many inflammatory mediators [prostaglandin E1 (PGE1), PGE2, TNF-α, IL-1, IL-6, IL-8, nitric oxide, and platelet-activating factor], and pathophysiological conditions (hypoxia, pulmonary hypertension) have been shown to induce the expression of VEGF, angiogenesis, or both." (PMID 17631682, 2007). "Therefore, IL-6 may be a promising therapeutic target for pulmonary arterial hypertension via regulation of intracellular IL-6 signaling." (PMID 34334083, 2021). "Moreover, IL-6 seems to have a strong impact on the development of pulmonary hypertension in COPD." (PMID 24739042, 2014). "Potential implications: IL-6 seems to be one of the most important inflammatory cytokines in the development of PAH, and in particular of hypoxia-induced pulmonary hypertension." (PMID 24739042, 2014). "Bosentan treatment has been shown to significantly reduce (ICAM‐1), IL‐6 and brain natriuretic peptide (BNP) in patients with pulmonary arterial hypertension." (PMID 40034063, 2025). "Notably, IL-6 stands out as a critical cytokine in the pathogenesis of PAH, as evidenced by the development of pulmonary hypertension symptoms in mice overexpressing IL-6, whereas IL-6-deficient mice do not develop pulmonary hypertension under hypoxic conditions." (PMID 39355239, 2024). "Numerous cytokines elevated in our study, such as IL-1α, IL-4, IL-5,IL-6, IL-7, IL-8, TNF-α were previously shown to involved in VOC-related acute clinical complications such as acute chest syndrome, pulmonary hypertension, and pulmonary thrombosis." (PMID 38361924, 2024). "It reduced the expression level of IL-6, TNF-α, and intercellular adhesion molecule-1 (ICAM-1) by regulating NF-kB signaling in pulmonary artery hypertension rat." (PMID 31024252, 2019). "Our aim is to assess the safety and potential efficacy of a novel treatment paradigm in pulmonary arterial hypertension (PAH), immunomodulation by blocking interleukin-6 (IL6) signaling with the IL6 receptor antagonist, tocilizumab." (PMID 28956500, 2018). "Liu and colleagues found that EP ameliorates monocrotaline-induced pulmonary arterial hypertension and reverses pulmonary vascular remolding in rats by inhibiting the release of TNF-α and IL-6 and by reducing the expression of endothelin-1." (PMID 25470819, 2014). "As suggested by recent publications, IL-6 might be one of the most important cytokines involved in the pathogenesis of PAH and hypoxia-induced pulmonary hypertension." (PMID 24739042, 2014). "This schematic illustrates the core mechanism in the pathogenesis of pulmonary arterial hypertension: Pulmonary vascular injury activates lung macrophages, releasing inflammatory mediators such as CCL2/CCL7, IL-1β/IL-6, and mitochondrial DAMPs into the circulatory system." (PMID 41479889, 2025). "Research has found a correlation between IL-6 and the development of hypoxia-induced pulmonary hypertension, but some studies have not shown a direct correlation between IL-6 concentration and mPAP or PVR indices." (PMID 37761997, 2023). "In patients with pulmonary arterial hypertension, Neb but not Met decreased the expression of pro-inflammatory cytokines, such as IL-6 and MCP-1, in pulmonary endothelial cells in a dose-dependent manner." (PMID 37998760, 2023). "•Plasma IL-6 & PTX3 were elevated in left heart failure and pulmonary hypertension." (PMID 38560419, 2022). "However, the mechanism by which IL-6 and TNF-α involved in pulmonary hypertension formation is unclear." (PMID 33971931, 2021). "Graham et al239 noticed that schistosoma-induced pulmonary hypertension in a model which lacked IL-6 signalling (at the level of either IL-6 or blocking STAT3) promoted the remodelling of the endothelial layer after S. mansoni exposure." (PMID 31024947, 2019). "In addition, A2BAR activation on pulmonary artery smooth muscle cells (PASMCs) results in increased IL-6 and hyaluronan, and deletion of A2BAR in these cells leads to reduced severity of pulmonary hypertension." (PMID 31379836, 2019).
pulmonary hypertension (continued). "These previous studies suggest that IL-6, TNF-α, and IL-1β may be actively involved in pulmonary hypertension." (PMID 31815093, 2019). "This may in part explain how soluble factors, such as IL-6, contribute to T helper 17 cell (TH17) activation and the M2-like macrophage response in hypoxia-induced pulmonary hypertension." (PMID 30081463, 2018). "Research focusing on the pathway of IL-6, involving the action of microRNAs and regulation of the expression of BMPR2 thus is ongoing to extend these findings to other forms of pulmonary hypertension or the use of these factors as surrogate markers for the disease." (PMID 24739042, 2014). "COPD patients with pulmonary hypertension had higher plasma levels than those without pulmonary hypertension and the levels of IL-6 correlated with the mPAP." (PMID 24739042, 2014). "Interestingly, HbSS patients with pulmonary hypertension had higher levels of various inflammatory cytokines (IL-6, 8 and 10) than HbSS without pulmonary hypertension." (PMID 38891066, 2024). "Tocilizumab did not block IL-6 signalling in pulmonary arterial hypertension." (PMID 34588193, 2022). "Alteration in chemerin signaling has already been linked to other pro-inflammatory conditions or cytokines (including TNF-α, IL-1β, and IL-6) upregulating CMKLR1 and CCRL2 which are also known to play crucial roles in pulmonary artery remodeling in pulmonary hypertension." (PMID 32848866, 2020). "Although serum level of IL-6 has never been studied in dogs with HWD, a recent study found that CRP levels were significantly higher in dogs with HWD and were closely correlated to the severity of pulmonary hypertension." (PMID 29143684, 2017). "However, only crp remained as an independent variable in the multiple regression analyses to predict LV function, in contrast to a previous study, showing that IL-6 was higher in COPD-PH than COPD-non-PH, and a correlation with severity of pulmonary hypertension." (PMID 32673327, 2020).
Abdominal obesity (132 papers, 2006 to 2025). Excessive fat around the stomach and abdomen. "Subcutaneous adipose tissue, especially in abdominal obesity, releases IL‐6 at higher levels, and genetic variability in the IL‐6 gene is associated with adiposity." (PMID 40551726, 2025). "For example, tumor necrosis factor and interleukin 6 play a role in promoting osteoclast differentiation, but these factors are associated with abdominal obesity." (PMID 37805606, 2023). "In a study of postmenopausal women, elevated IL-6 was also associated with abdominal obesity, low HDL, and high triglycerides." (PMID 35050195, 2022). "IL-6 has been found to increase in MetS and is associated with central obesity, low HDL, and high TG." (PMID 36358526, 2022). "Our results suggested that the C allele of rs1800796 and the C allele of rs2069849 of IL-6 gene interaction between rs1800796 and abdominal obesity were all associated with increased OST risk." (PMID 31301734, 2019). "Risk genotype carriers who were also homozygous for the IL-6 rs1800797 G allele were most at risk of developing the MetS (OR 2.10), fasting hyperglycaemia (OR 2.65) and abdominal obesity (OR 1.52)." (PMID 23306188, 2013). "Our results clearly demonstrated association between hs-CRP/IL-6 levels and clustering of MetS components predominantly in the presence of abdominal obesity." (PMID 17903275, 2007). "In agreement with previous reports, low level of serum adiponectin is a potent risk for MetS, and elevation of serum hs-CRP and IL-6 concentration enhances the incidence of MetS in the subjects with abdominal obesity." (PMID 17903275, 2007). "The mechanism behind this could be due to pro-inflammatory cytokines associated with abdominal obesity, such as tumor necrosis factor-alpha and interleukin-6 (IL-6)." (PMID 37764873, 2023). "Moreover, IL-6 and resistin have been associated with abdominal obesity on the one hand and an increased number of senescent T cells on the other hand." (PMID 33922813, 2021). "IL-6 present in ductal lavage fluid could reflect local inflammation at the breast or systemic inflammation known to be linked to excess abdominal obesity." (PMID 23217221, 2012). "However, serum levels of hs-CRP and IL-6 significantly increased in association with clustering of MetS components in abdominal obesity group." (PMID 17903275, 2007). "Lastly, abdominal obesity is often accompanied by chronic low-grade inflammation, characterized by elevated inflammatory markers like C-reactive protein and interleukin-6." (PMID 40092916, 2025). "The explanation for the correlation of neck circumference and blood pressure is that central obesity as reflected by increased neck circumference gives rise to the release of some inflammatory cytokines such as tumor necrosis factor-α and IL-6." (PMID 40519810, 2025). "This study underscores the importance of IL‐6 in improving LV GLS in individuals with abdominal obesity suggesting a role for IL‐6 in cardiac functional exercise adaptations." (PMID 38803062, 2024). "Abdominal obesity is linked to the production of inflammatory cytokines and adipokines, such as TNF-α, IL-6, adiponectin and leptin, which can be involved in kidney damage." (PMID 38559695, 2024). "In abdominal obesity, visceral fat produces pro-inflammatory cytokines, known as adipocytokines, including leptin, resistin, visfatin, interleukin 6 (IL-6), and tumor necrosis factor α (TNF-α), which influence systemic inflammation and insulin sensitivity." (PMID 39767613, 2024). "Visceral adipocytes stimulate the production of several cytokines, including interleukin-6 and tumor necrosis factor-alpha, in patients with abdominal obesity, which encourages macrophage infiltration and persistent inflammation." (PMID 39511357, 2024). "In another, GH treatment in postmenopausal women with abdominal obesity reduced their serum markers of C-reactive protein and IL-6." (PMID 38405219, 2024).
Abdominal obesity (continued). "Stimuli including bad eating habits, increased abdominal obesity, sedentary lifestyle, smoking, and alcohol consumption increase the release of proinflammatory factors such as IL-6 and IL-18 from various tissues." (PMID 37736511, 2023). "The previous finding was challenged by a study showing that, in the presence of abdominal obesity, the contribution of visceral adipose tissue to circulating levels of IL-6 was modest, although IL-6 concentrations are increased in the systemic circulation." (PMID 34372491, 2021). "Such outcome was also found between abdominal obesity and circulating levels of IL-6 in another study." (PMID 34957175, 2021). "Abdominal obesity leads to an imbalance in the production and secretion of pro-inflammatory (IL-6, IL-1β, TNF-α) and anti-inflammatory (IL-10) factors, and contributes to the occurrence of chronic, low-grade systemic inflammation." (PMID 32872598, 2020). "Taking this into account, the aim of this study is to analyse the eating habits related to calorie intake and its impact on the abdominal obesity associated with anthropometric variables, PON1 activity and IL-6 levels in serum." (PMID 32168955, 2020). "The reduction of high-density lipoprotein cholesterol (HDL-C) suppresses osteogenic activity in vascular cells, and abdominal obesity increases inflammatory cytokines such as interleukin-6 (IL-6) and tumor necrosis factor alpha (TNF-α)." (PMID 31341843, 2019). "Some studies indicated that gene expression and production of IL-6 and TNFα are elevated in general and abdominal obesity." (PMID 31272370, 2019). "Once beyond the specific cutoff for waist circumference to be defined as central obesity, multiple cardiovascular risk factors begin to appear, and therefore, CRP and IL-6 were rapidly reaching remarkably high circulating levels in individuals with MetS." (PMID 29670915, 2018). "The main effects of central obesity were observed on insulin (Wald chi square = 17.4, P < 0.001), chemerin (Wald chi square = 4.7, P = 0.031), IL-6 (Wald chi square = 7.6, P = 0.001), and PAI-1 (Wald chi square = 5.9, P = 0.016)." (PMID 30114249, 2018). "Abdominal obesity, assessed as waist circumference, has been found to explain most of the variance in IL-6 levels after adjustment for age, sex, smoking habits, alcohol consumption, and physical activity level." (PMID 27567677, 2016). "Central obesity has been recognized as significant predictor of high IL-6 levels in the circulation even after adjustment for markers of lipid and glucose metabolism, blood pressure, smoking status, sex and age." (PMID 27567677, 2016). "Abdominal obesity, a key component of MetS, is consistently associated with major increases in pro-inflammatory adipocytokines, such as TNF-α, IL-6, hsCRP or PAI-1 active, as well as reduced protective cytokines, such as adiponectin, agreeing with our data." (PMID 25407698, 2014). "Men in the subgroup of increased ba-PWVs showed significant increases in abdominal obesity, which were correlated with increases in IL-6 and the ratio of TCI/TEE (the ratio of total calorie intake to total calorie expenditure)." (PMID 22806411, 2013). "Coronary artery calcification, increasing levels of IL-6, abdominal obesity, lower HDL cholesterol, and albuminuria were significantly associated with greater ssEFV." (PMID 23351146, 2013). "Additionally, central obesity correlates with increased inflammatory markers, such as C-reactive protein and interleukin-6, which contribute to atherosclerotic plaque instability and vascular remodeling." (PMID 40013043, 2025). "Collectively, this perturbation in monocyte biology may explain the more pro‐inflammatory phenotype in SAs compared with WEs, with studies reporting higher CRP and IL‐6 concentrations in healthy middle‐aged SA men, women, and men with central obesity." (PMID 38011590, 2023).
Abdominal obesity (continued). "Additionally, leptin, adiponectin, resistin, TNF-α, IL-6, and other metabolic substances are related to the relationship between abdominal obesity and BMD." (PMID 36313427, 2022). "Moreover, another population-based study (n = 740) revealed that abdominal obesity correlated with IL-6 and CPR." (PMID 33946540, 2021). "This seems to favour the abdominal obesity associated with high values of proinflammatory IL-6 that is not correlated with a lower activity of PON1." (PMID 32168955, 2020). "This seems to favour abdominal obesity associated to high values of proinflammatory interleukin 6, which, however, is not correlated with a lower activity of the oxidation marker PON1." (PMID 32168955, 2020). "The average levels of IL-6 are significantly higher when patients have abdominal obesity." (PMID 32168955, 2020). "The aim of this study was to analyse the eating habits related to calorie intake and their impact on abdominal obesity associated with anthropometric variables, the activity of the oxidation marker paraoxonase 1 (PON1), and interleukin 6 (IL-6) levelsin MS patients." (PMID 32168955, 2020). "In addition we propose that further work is necessary to explore the potential significance of central obesity on the levels of IL-6." (PMID 24895539, 2014). "Exercise, coupled with interventions specifically targeting abdominal obesity and IL-6 and adiponectin concentrations may be most effective at correcting total WBC counts by independently lowering lymphocyte, monocyte, and basophil numbers." (PMID 22363616, 2012). "In particular, the altered pattern of adipocytokine secretion characterizing central obesity—that is, reduced adiponectin and elevated levels of leptin, resistin, TNFα, and IL-6—increases the production of superoxide anion (O2−), that interferes with NO availability, thus reducing vasodilation." (PMID 20652043, 2010). "Serum levels of hs-CRP and IL-6 significantly increased in association with clustering of MetS components in the subjects with abdominal obesity, but not in those without abdominal obesity." (PMID 17903275, 2007). "Interestingly, in non-abdominal obesity group, serum levels of hs-CRP and IL-6 changed a little in association with clustering of MetS components." (PMID 17903275, 2007). "Moreover, after the intervention, subjects in the marine omega-3 group had a higher reduction in the prevalence of abdominal obesity compared to the active placebo group, and better differences between IL-6, IL-10, MCP-1, and RvD1 changes at the end of the study." (PMID 39857130, 2025). "Moreover, after adjustment for age, BMI, and gender, the levels of TNF-α, IL-6, and ROS were associated with central obesity but not general obesity." (PMID 25918477, 2015). "Central obesity leads to excessive secretion of pro-inflammatory mediators like leptin, TNF-α, and IL-6, thus escalating systemic inflammation and vascular injury." (PMID 40606025, 2025). "Heightened secretion of IL-6, TNF α, and C-RP is evident in individuals with abdominal obesity, intensifying the inflammatory state." (PMID 40310144, 2025). "Abdominal obesity is characterized by an excess of visceral fat, which secretes pro-inflammatory cytokines such as TNF-α, IL-6, and CRP." (PMID 39450238, 2024). "IL-6 is produced by adipose tissue and the mean values for WC and WHR herewith are indicative of abdominal obesity." (PMID 37608129, 2024). "Our results show that increases in adipokines (PAI-1, IL-6, and chemerin), which favour the differentiation of preadipocytes attributed to the effect of central obesity, might represent the first-line adipokines that initiate subsequent inflammatory cascades in individuals with only central obesity." (PMID 30114249, 2018). "High levels of inflammatory markers such as IL-6, tumor necrosis factor, and CRP are related to general and abdominal obesity." (PMID 25874126, 2015).